LRRC30 (leucine rich repeat containing 30)
Tractability: No criterion of Open Targets' tractability assessment is met for any kind of drug.
Gene: Protein-coding gene on chromosome 18 (7,231,089 to 7,232,044, forward strand). Ensembl gene ENSG00000206422.
Gene Ontology:
Biological process: intracellular signal transduction
Genetic constraint (gnomAD): Loss-of-function variants: 10 observed, 15.34 expected, observed/expected ratio (o/e) 0.65, 90% interval 0.4 to 1.11. The upper end of that interval is the gene's LOEUF score, 1.11, which puts it in group 4 of 6, group 1 being the genes least tolerant of losing a copy. Missense variants: 403 observed, 391.59 expected, observed/expected ratio (o/e) 1.03, 90% interval 0.95 to 1.12. Synonymous variants: 202 observed, 187.05 expected, observed/expected ratio (o/e) 1.08, 90% interval 0.96 to 1.21.
Homologues: Orthologues: chimpanzee LRRC30 (99% identical), macaque LRRC30 (98% identical), mouse Lrrc30 (88% identical), rabbit LRRC30 (88% identical), rat Lrrc30 (88% identical), dog LRRC30 (83% identical), zebrafish lrrc30a (29% identical), Drosophila melanogaster f-cup (29% identical), Drosophila melanogaster CG3494 (23% identical). Paralogues in human: SCRIB (30% identical), LRRC8C (27% identical), LRRC8D (27% identical), LRRC1 (26% identical), LRRC8E (26% identical), LRRD1 (26% identical), LRRIQ4 (26% identical), ERBIN (26% identical), LRRC40 (26% identical), PHLPP2 (26% identical), LRRC8A (25% identical), LRRK1 (25% identical), and 19 more.
Diseases named in the same sentence as LRRC30 in open-access papers:
LRRC30 is named in the same sentence as 3 diseases in open-access papers, as found by Europe PMC text mining. Sharing a sentence is not in itself a finding about the gene and the disease.
LRRC30 shares sentences with these, for which no sentence is quoted: Autoimmunity (1 paper); pancreatic tumor (1); thyroid disease (1).